FMR1 (fragile X messenger ribonucleoprotein 1)
Diseases named in the same sentence as FMR1 in open-access papers (continued):
Sharing a sentence is not in itself a finding about the gene and the disease.
Cognitive impairment (continued). "Thus, the overexpression of ICAM5 in postnatal development in Fmr1 KO mice may be a neurobiological mechanism for FXS pathological phenotypes and a therapeutic target for the treatment of FXS cognitive impairment." (PMID 31882402, 2020). "Aside from obviously elevated FMR1 mRNA levels, reduced FMRP expression, and intranuclear inclusion formation, mouse models of FXTAS also exhibit abnormal dendritic spine morphology, impaired motor coordination, and cognitive deficits, recapitulating many features of FXTAS patients." (PMID 28529475, 2017). "While there are some reports of background strain-dependent phenotypes in the Fmr1 mouse, a recent review of the effect of background strain on cognitive abilities in Fmr1 mice did not reveal consistency in strain-specific cognitive deficits." (PMID 27022628, 2016). "We hypothesized that challenging touchscreen paradigms of working memory would detect cognitive deficits in Fmr1 mice that were not detectable with arguably simpler tasks in the literature." (PMID 27022628, 2016). "Our current hypothesis is that activation of 5-HT7 receptors, by correcting mGluR-mediated mechanisms in Fmr1 KO mice, besides reversing abnormal mGluR-LTD can also rescue other typical phenotypes of FXS, particularly abnormal dendrite morphology, cognitive impairment and autistic behavior." (PMID 25814945, 2015). "However, treating the Fmr1 KO mice with bryostatin-1 for 5 weeks, a timescale comparable to several months of human treatment, had very limited or no therapeutic effects on the behavioral and cognitive deficits." (PMID 37351510, 2023).
autism spectrum disorder (87 papers, 2005 to 2025). A spectrum of developmental disorders that includes autism, and Asperger syndrome. "Specifically, enhanced hippocampal gamma oscillations and their aberrant synchronization have been implicated in reduced cognitive flexibility in the Fmr1 KO mice and autism spectrum disorders." (PMID 41177899, 2025). "The FMR1 gene in its premutation (PM) state has been linked to a range of clinical and subclinical phenotypes among FMR1 PM carriers, including some subclinical traits associated with autism spectrum disorder (ASD)." (PMID 34421690, 2021). "Although the causal relationship is still unclear, fmr1-KO mice, an animal model of autism spectrum disorders, show abnormal spine configurations (elongated spines and increased density) and also show the enhanced mGluR-dependent LTD in the hippocampus." (PMID 30349460, 2018). "Likewise, it was recently shown that FMRP regulates alternative splicing and that in Fmr1 knockout (KO) mice, alternative splicing is deregulated, affecting genes associated with autism spectrum disorder, similar to the findings of Sharon and colleagues." (PMID 39596472, 2024). "Although FMR1 mutations are associated with autism-spectrum disorders, which is characterized by repetitive or compulsive behaviors, we considered the marble burying test adequate to control for the willingness to dig, since these are natural and spontaneous behaviors in mice." (PMID 37542065, 2023). "Mutations in FMR1 are the most common heritable cause of autism spectrum disorder." (PMID 35731217, 2022). "First, Fmr1 mutations and other autism spectrum disorder gene defects may indirectly regulate mitochondrial protein composition at steady state." (PMID 33931071, 2021). "Since mitochondrial ontologies were revealed by their TTX-APV treatment rather than the Fmr1 genotype, we further inquired whether mitochondrial genes were annotated either to autism spectrum disorder curated databases or whether mitochondrial nuclear encoded mRNAs were bound by FMRP." (PMID 33931071, 2021). "Intriguingly, increased DOPAC/DA were described in the cortex, striatum, and hippocampus of the Fmr1-KO mouse model of autism spectrum disorder, characterized by social deficits opposite to the hypersociability of CD mice." (PMID 41154609, 2025). "In vitro and ex vivo studies have shown consistent indications of hyperexcitability in the Fragile X Messenger Ribonucleoprotein 1 (Fmr1) knockout mouse model of autism spectrum disorder." (PMID 38771240, 2024). "FXS, the most common single-gene cause of autism spectrum disorder (ASD), is characterized by an expansion of the CGG triplet in the FMR1 gene, leading to the loss of the FMR1 protein)." (PMID 37445940, 2023). "A further example involves rat models of autism spectrum disorder where Fragile X messenger Ribonucleoprotein 1 (Fmr1) knock out rats pups spend less time playing with fewer ultrasonic communications, as well as other repetitive behaviors." (PMID 35948659, 2023). "FXS is the most frequent monogenic autism spectrum disorder (ASD), accounting for 2% of all cases, and is caused by a mutation in the fragile X mental retardation 1 (FMR1) gene which causes loss of FMRP protein." (PMID 33809142, 2021). "An enhanced expression of mGlu5 receptors has also been found in Fmr1 knockout mice, as well as in brain tissues from children affected by autism spectrum disorder." (PMID 29615849, 2018). "These flies exhibited behavioral characteristics similar to those observed in human autism spectrum disorder patients, and showed excessive synaptic satellite bouton outgrowths, similar to those in Fmr1 mutants." (PMID 29295819, 2018). "This study was designed to test a new approach to drug treatment of autism spectrum disorders (ASDs) in the Fragile X (Fmr1) knockout mouse model." (PMID 25705365, 2015).
autism spectrum disorder (continued). "Atypical visual attention patterns have been observed among carriers of the fragile X mental retardation gene (FMR1) premutation (PM), with some similarities to visual attention patterns observed in autism spectrum disorder (ASD) and among clinically unaffected relatives of individuals with ASD." (PMID 33633778, 2021). "Indeed, mice with reduced expression of the NMDAR subunit, GluN1 exhibit a range of behavioral phenotypes that are not only consistent with autism spectrum disorder, but also which overlap with those observed in Fmr1 KO mice." (PMID 29062097, 2017). "Fragile X syndrome (FXS), the leading monogenetic cause of intellectual disability (ID) and autism spectrum disorder (ASD), results from excessive trinucleotide cytosine–guanine–guanine (CGGn) repeats in the promotor region of the fragile X mental retardation 1 (FMR1) gene." (PMID 35326270, 2022). "Interestingly, Fmr1 KO mice showed a preference for the familiar compared to the novel object, consistent with previous studies demonstrating alterations of novelty preferences, with stereotyped behavior and restricted interests, in autism spectrum disorders." (PMID 30333723, 2018). "The search terms "Fragile X mental retardation 1 (FMR1) gene", "Cytosine-guanine-guanine (CGG) repeats", "Autism spectrum disorder", and "Fragile X syndrome (FXS)" were used, and the obtained studies were assessed for suitability." (PMID 37007359, 2023). "There have been clinical and community-based studies of FMR1 premutation carriers that suggest the FMR1 premutation may increase the risk of Fragile X-associated neuropsychiatric disorders (FXAND) and conditions (FXPAC), including attention deficit disorder (ADHD) and autism spectrum disorder (ASD)." (PMID 37628570, 2023). "Thirty‐six patients with ID, 12 with autism spectrum disorder (ASD) and 13 females with idiopathic POI were screened for FMR1 CGG repeat size by fluorescent methylation‐specific PCR and GeneScan analysis, irrespective of Hagerman checklist clinical scores." (PMID 36618123, 2021). "Lesions that silence the fmr1 gene, which encodes FMRP, cause Fragile X syndrome and are linked to autism spectrum disorder and mice lacking FMRP show increased levels of protein synthesis and supernumerary dendritic spines." (PMID 24347626, 2014). "Interestingly, Fmr1 KO mice presented less spontaneous freezing behavior compared to WT, consistent with previous studies in GAP43 mice model of autism spectrum disorder and probably reflecting some aspects of maladaptive behavior to stress and catatonia in patients." (PMID 30333723, 2018). "In fact, findings from FMR1 Knockout (FMR1-KO) mice and genetic deletion studies support the hypothesis that aberrant regulation of mGluR5 can lead to developmental synaptic disorders such as FXS or autism spectrum disorder and hence can serve as a target for interventions." (PMID 35582646, 2022).
Ataxia (45 papers, 2008 to 2025). Ataxia refers to impaired coordination of voluntary muscle movement. "In summary, our work reveals extensive FMR1 somatic mosaicism in Fragile-X associated tremor/ataxia syndrome in human brain." (PMID 41278766, 2025). "FXTAS is associated with elevated levels of FMR1 mRNA, leading to neurodegenerative manifestations such as tremors and ataxia." (PMID 38578387, 2024). "The core clinical manifestations of FMR1 premutation alleles were cerebellar ataxia and action tremor; specifically, about one-third of those affected presented with Parkinsonian symptoms." (PMID 37583466, 2023). "Participants included 152 female FMR1 PM carriers and 75 female controls who were similar in age and IQ, and screened for neuromotor impairments or signs of fragile X-associated tremor/ataxia syndrome." (PMID 34421690, 2021). "A large investigation by Kamm and coworkers (2005) showed that FMR1 premutation-associated ataxia is distinct from MSA-C." (PMID 26331038, 2014). "Expansion of CGG repeats (CGGexp) in the 5’ untranslated region (5’UTR) of the FMR1 gene underlies the fragile X premutation-associated conditions including tremor/ataxia syndrome, a late-onset neurodegenerative disease and fragile X-associated primary ovarian insufficiency." (PMID 40377206, 2025). "Because Fmr1 mutation causes a tremor/ataxia phenotype and the Fmr1 gene is located in the candidate region, we excluded the Fmr1 repeat expansion as a causative mutation for the shaker rat by amplification and sequencing of the 5′-UTR region that contains the CGG repeat." (PMID 27013529, 2016). "Premutation and full-mutation hyperexpansion of CGG-triplets in the X-linked Fragile X Mental Retardation 1 (FMR1) gene have been implicated in fragile X-associated tremor/ataxia syndrome, fragile X-associated primary ovarian insufficiency, and fragile X syndrome (FXS), respectively." (PMID 25936533, 2015). "A premutation of the FMR1 gene causes a late onset form of ataxia called FXTAS." (PMID 26331038, 2014). "The atypical clinical phenotypes of FXTAS, particularly in the female patients, highlighted the necessity of genetic testing of FMR1 premutation from patients with undiagnosed ataxia." (PMID 34498198, 2022). "Apart from classical FMR1 disorder symptoms (tremor and ataxia), ovarian dysfunction is also common." (PMID 34362406, 2021). "This is comparable to the pooled prevalence of FXTAS in male cerebellar ataxia patients, which is 1.5% (16/1049), reported in a meta‐analysis of FMR1 premutation screening studies (Jacquemont, Leehey, Hagerman, Beckett, & Hagerman, 2006)." (PMID 31158927, 2019). "Below, we have focused on the well-studied protein FMRP encoded by the fragile X mental retardation gene 1 (FMR1), the causative gene of FXS and fragile X-associated tremor/ataxia syndrome." (PMID 31200506, 2019). "We suggest that patients with primary ovarian insufficiency, tremor and/or ataxia should be suspected of having premutation of the FMR1 gene." (PMID 29299012, 2017). "The frequency of FMR1 premutations was 1.9% (1/54) in our group of patients with ataxia as the primary clinical feature, and 1.2% (1/86) in the larger movement disorders group." (PMID 21639881, 2011). "The frequency of FMR1 premutations was 1.9% (1/54) in patients with ataxia as the cardinal clinical feature, which is within the range reported by multiple studies (0% to 4.1%), and 1.2% (1/86) in our global sample." (PMID 21639881, 2011). "A review of the literature reported that the frequency of FMR1 premutations, in all combined ataxia cases, was 1.3% in men and 0.24% in women." (PMID 21639881, 2011). "Although the X chromosome carries the FMR1 gene – implicated in Fragile X–associated tremor/ataxia syndrome (FXTAS) – ataxia in KS does not appear to be related to FMR1 repeat expansions." (PMID 41357298, 2025).
Ataxia (continued). "The fragile X mental retardation 1 gene (FMR1) produces multiple APA transcript isoforms in Fragile X syndrome (FXS) and related diseases, such as fragile X-associated immature ovarian insufficiency and fragile X-associated tremor and/or ataxia syndrome." (PMID 32560344, 2020). "As ataxia in FXTAS is often associated with tremor and/or cognitive decline, it is plausible that some cases of FXTAS could present for testing with a clinical diagnosis other than cerebellar ataxia; therefore, other movement disorders have also been screened for FMR1 premutations." (PMID 21639881, 2011). "Considering that the symptoms of PD, essential tremor (ET), and spinocerebellar ataxia (SCA) overlap to some extent with those of FXTAS, previous studies have screened these patients for CGG repeat expansion of the FMR1 gene." (PMID 37583466, 2023). "Twenty percent of PM females manifest an FMR1-related POI, while FXTAS occurs in PM males (rarely in females) and is characterized by late-onset, progressive cerebellar ataxia and intention tremor." (PMID 28420439, 2017). "Importantly none of the individuals carrying FMR1CRE showed signs of FRAX Tremor and Ataxia Syndrome (FRAXTAS [OMIM #300623]; FMR1 over-expression)." (PMID 34388204, 2021). "Here, we present the first study on the frequency of FMR1 premutations in a sample of Portuguese males sent for genetic testing, with late-onset movement disorders characterized by one or more of the FXTAS cardinal clinical features (ataxia, tremor, or cognitive decline)." (PMID 21639881, 2011). "However, we found no FMR1 premutations in 32 patients with a movement disorder other than ataxia, which is consistent with the literature." (PMID 21639881, 2011).
Rett syndrome (36 papers, 2010 to 2025). A severe neurodevelopmental disorder affecting the central nervous system.
schizophrenia (36 papers, 2011 to 2025). A major psychotic disorder characterized by abnormalities in the perception or expression of reality. "FMR1 mutations have been linked with cognitive impairment and earlier age of onset in schizophrenia." (PMID 31078131, 2019). "Inhibiting PDE2A improves social recognition memory, lessens social withdrawal behavior in a rodent model of schizophrenia, and rescues social deficits in Fmr1 KO animals." (PMID 34887755, 2021). "It would thus be premature to conclude that changes in FMR1 targets identified in schizophrenia results from altered FXR1 functions since these two proteins are not biologically equivalent." (PMID 30687136, 2018). "In contrast to FMR1, FXR1 came out of the shadow after its identification as one of the top 30 potential genetic risk factor for schizophrenia." (PMID 30687136, 2018). "Altered FMRP levels have also been observed in disorders unassociated with an expansion in Fmr-1, such as schizophrenia, bipolar disorder, major depression, autism spectrum disorder, and epilepsy." (PMID 26580204, 2015). "The association of low FMRP with psychotic features is becoming more intriguing since FMRP deficits correlate with earlier age of onset and lower IQ in those with schizophrenia without a FMR1 mutation." (PMID 32576818, 2020). "In addition to schizophrenia, some studies indicated that Fmr1 targets are enriched within genes that are shown to be affected in bipolar patients." (PMID 30087606, 2018). "Furthermore, recent large-scale studies indicated enrichment of Fmr1 targets in the genetic architecture of schizophrenia." (PMID 30087606, 2018). "Furthermore, a postmortem study has shown altered protein levels of FMR1 targets in the frontal cortex of subjects with schizophrenia or bipolar disorder." (PMID 30687136, 2018). "It is interesting that a recent report of FMRP levels in neuropsychiatric disorders without an FMR1 mutation demonstrated very low levels of FMRP in the brains of people with schizophrenia and people with autism." (PMID 21303513, 2011). "Polymorphisms in the Fxr2 and Fmr1 loci have not been associated with schizophrenia by GWAS." (PMID 30087606, 2018). "Using the PGC2 secondary analysis schizophrenia case-control cohort (N = 29,125 cases and 34,836 controls), a robust polygenic signal was observed from gene sets based on TCF4, FMR1, upregulation from MIR137 and downregulation from CHD8." (PMID 31078131, 2019). "Both miRNAs overlapped by the 3q13.31 deletion in this patient (miR-4796, miR-568) have predicted targets that are additional candidate genes for schizophrenia and related disorders, including SHANK2 and FMR1." (PMID 24650298, 2014).